CALR (calreticulin)
Diseases named in the same sentence as CALR in open-access papers (continued):
Sharing a sentence is not in itself a finding about the gene and the disease.
cancer (continued). "In the unpaired BLCA samples, compared to adjacent tissues, carcinoma tissues expressed higher levels of CALR." (PMID 38023241, 2023). "The translocation of calreticulin from the endoplasmic reticulum to the cell surface has been reported to be crucial for cancer cell immunogenicity and CD8 + mediated destruction." (PMID 35659676, 2022). "Cellular stress can move CALR fragments to the plasma membrane from the ER and influence immune recognition of cancer cells." (PMID 35982973, 2022). "Our experimental results showed that curcumin significantly enhanced IR-induced calreticulin exposure, which was a powerful “eat me” signal that interacted with phagocytes to assist in phagocytosis of cancer cells." (PMID 36238646, 2022). "Across a variety of cancers, eIF2α phosphorylation is positively correlated with calreticulin (CRT) exposure, higher tumor immune infiltration (by dendritic cells (DCs) and cytotoxic T lymphocytes (CTLs)) and better clinical outcome in patients." (PMID 36010596, 2022). "Calreticulin expression is increased in a range of cancers, including leukemias, bladder cancer, and ovarian cancer, whereas SLAMF7 expression is increased in predominantly hematopoietic tumor cells." (PMID 35865547, 2022). "Immunostimulatory danger-associated molecular patterns (DAMPs) (such as ANXA1, CALR, and HMGB1) and cytokines (such as IFN and CXCL10) were used to evaluate the immunogenicity of cancer cell death." (PMID 36003383, 2022). "Second, ICD leads to the translocation of calreticulin (CRT) into the surface of cancer cells, which releases the “eat me” signal for DCs." (PMID 36131787, 2022). "The article entitled “Calreticulin exposure dictates the immunogenicity of cancer cell death” by Obeid M had the most co-citations (n = 547)." (PMID 36278159, 2022). "Because of its multifunction, previous studies have shown a contributing role for CALR in various diseases, including neurodegenerative problems, cancers, autoimmune diseases, and wound healing." (PMID 35641480, 2022). "In comparison with GTEx and TCGA normal, the robust expression of CALR was also witnessed in TCGA cancer samples, including LUAD and LUSC." (PMID 35264066, 2022). "The targeted nanoclusters, anti-CRT-AuNCs, were previously shown to bind to HT29 and MCF7 cancer cells lines, grown in 2D monolayer cultures, demonstrating the potential of calreticulin as a cancer biomarker." (PMID 39872615, 2022). "To evaluate CALR expression in various human cancers, we examined the CALR expression in multiple cancers using the TIMER database." (PMID 36338983, 2022). "Bioinformatics analysis illustrated upregulation of CALR expression in pan-cancer cohort, including LUAD and LUSC." (PMID 35264066, 2022). "Calreticulin are recognised as “eat me” signals, promoting the phagocytosis of cancer cells by the immune system." (PMID 35665592, 2022). "In many cancers, calreticulin is exposed in the cell surface that would indicate an “eat-me” signal." (PMID 35421980, 2022). "An “Eat me signal” calreticulin secreted or exposed on the cell surface of cancer cells allows macrophages to recognize and phagocytose them." (PMID 36679900, 2022). "On the other side, cell surface calreticulin ensures the phagocytic removal of dying cancer cells by a subset of DCs, being a pre-requisite for the development of adaptive anticancer immunity." (PMID 35190586, 2022). "Genetic knockdown or antibody ablation of calreticulin attenuated the phagocytosis of cancer cells by APCs, resulting in the elimination of cancer cell immunogenicity." (PMID 35432318, 2022). "This group was suggested to be in an immunoediting step of cancer elimination: they can mount strong CALR-specific responses but cannot eliminate all mutant cells." (PMID 35603202, 2022). "Over the past years, numerous studies have demonstrated that CALR participated in various cancer cell invasion and migration and was related to patients’ unfavorable clinical prognosis." (PMID 35641480, 2022).
cancer (continued). "Among all of the ICD-related genes, CALR showed the highest expression in pan-cancers, while IFNB1 showed the lowest expression." (PMID 36497433, 2022). "The overexpression of surface CALR has been demonstrated in several types of cancer cells and also on leukemic blasts and AML-SCs in adult AML compared with healthy control HSCs." (PMID 35892824, 2022). "Glycolysis inhibitors, in combination with cytotoxic agents, can convert conventional cancer cell death into ICD through ERp57/calreticulin exposure on the plasma membrane." (PMID 35665592, 2022). "Surface exposed calreticulin for example promotes tumor antigen presentation by facilitating DC phagocytosis, but can also promote cancer cell invasion." (PMID 35046546, 2022). "Calreticulin (CRT), an endoplasmic reticulum–resident protein generally overexpressed in cancer cells, is associated with radiation resistance." (PMID 34472223, 2022). "KEGG Pathway Analysis revealed that overexpression of CALR remarkably affected cellular focal adhesion and pathways in cancer." (PMID 35641480, 2022). "These drugs stimulate cancer cells to release damage-related model molecules, including calreticulin (CRT), adenosine-triphosphate (ATP), high mobility group protein B1 (HMGB1), CXCL1, and CCL2." (PMID 35635307, 2022). "Nonetheless, the role of CALR in cancers is inconclusive considering the CALR gene regulating intracellular Ca2+ balance and integrin-dependent events." (PMID 35264066, 2022). "Calreticulin exposure on the cell surface has been identified as a crucial feature in determining the immunogenicity of cancer cell death." (PMID 33478072, 2021). "Calreticulin has an important impact in the cancer development and their expression levels affects the cell proliferation, differentiation and angiogenic capacity, and its interaction with integrins impact on cell adhesion and ultimately in the metastasis." (PMID 33656060, 2021). "Beginning with calreticulin (CALR), an abundant endoplasmic reticulum (ER) protein, ER stress induced by ICD inducing agents cause CALR to translocate to the plasma membrane of dying cancer cells." (PMID 34869014, 2021). "In mouse models CALR release was confirmed with extracellular CALR performing immunomodulatory properties and inhibiting the phagocytosis of dying cancer cells." (PMID 33806036, 2021). "Recent studies suggested that calreticulin (CRT) has an important role in the progression of various types of cancer." (PMID 33591948, 2021). "On the other hand, cell surface calreticulin is shown to present two opposing functions, stimulating phagocytosis to remove cancer cells as well as efferocytosis to silence immune responses." (PMID 33859739, 2021). "The NGS analyses identified mutations in eight cancer associated genes: ESR1, MECOM, JAK3, KMT2C, CTNNB1, CALR, NCOR1 and AMER." (PMID 34209696, 2021). "Taking into account that doxorubicin, that is, the cytotoxic payload of Doxil, induces immunogenic cell death, we sought to examine the immunogenic effects of Doxil on metastasis via quantification of the surface calreticulin (CRT) on dying cancer cells." (PMID 33552852, 2021). "Pro-phagocytic signals such as calreticulin and phosphatidylserine on cancer cells were considered to accelerate cancer cell-specific phagocytosis." (PMID 33799989, 2021). "Therapeutic cancer vaccination with peptide vaccines derived from mutant CALR with montanide as an adjuvant, is safe and tolerable." (PMID 33718228, 2021). "Immunohistochemical analysis was conducted to assess the intensity of membranous- and intracellular-located calreticulin in cancer cells." (PMID 33920544, 2021). "CALR exposure on the surface of dying cancer cells induces phagocytic uptake by dendritic cells and is a hallmark of immunogenic cell death (ICD)." (PMID 34944059, 2021). "CALR-exposing cancer cells deliver pro-phagocytic signals to antigen presenting cells (APCs) and activate dendritic cell efferocytosis." (PMID 33652860, 2021).
cancer (continued). "To investigate the role of CALR in cancers, we detected the CALR expression in 23 types of tumors and corresponding normal tissues using the UALCAN database." (PMID 34910788, 2021). "In cancer cells with apoptosis induced by chemotherapeutic agents such as anthracyclines and oxliplatin, calreticulin trafficks to the cell surface, dictating a process of immunogenic cell death (ICD)." (PMID 33790906, 2021). "Cancer cell surface–exposed calreticulin (ecto-CRT) is the primitive form of signal during immunogenic cell death (ICD)." (PMID 34199835, 2021). "A potential link between the upregulation of ICD-associated biomarkers and the recruitment of DCs to the TME in cancer patients has only been reported for calreticulin." (PMID 33920544, 2021). "In vivo, the augmented expression of calreticulin on the surface of cancer cells usually triggers a calreticulin-dependent mechanism of their immunogenic killing by cytotoxic T-lymphocytes." (PMID 32268506, 2020). "In immunodeficient mice, elevated exposure of calreticulin (CALR) on the cell membrane endows hyperploid cancer cells with immunogenicity, possibly by constitutively increasing endoplasmic reticulum (ER) stress." (PMID 32606370, 2020). "Therapeutic cancer vaccination against the JAK2V617F and CALR exon 9 driver mutations is likely to induce immune responses." (PMID 32630667, 2020). "Cancer cells tagged by calreticulin on their surface stimulate an immunogenic cancer cell death by enabling their phagocytosis by the dendritic cells of the immune system which in turn triggers T-cell-mediated immune response." (PMID 33110154, 2020). "Immunogenic cell death of cancer cells shortly after NIR-PIT releases damage-associated signals such as ATP, calreticulin, and high-mobility group box 1, which promotes DC maturation and subsequent effector T-cell activation mediated by IL-15." (PMID 32927646, 2020). "It is generally accepted that calreticulin is one of the cancer-promoting proteins because its high expression was shown to correlate with active cell proliferation in different types of cancer, with metastasis occurrence and with VEGF-stimulated angiogenesis." (PMID 32268506, 2020). "In this conjuncture, it would be worthwhile to investigate the frequency of certain HLA types in patients with CALR-mutant MPN, as it has been demonstrated that certain HLA types are underrepresented in cancers with immunogenic driver mutations." (PMID 32630667, 2020). "Anthracyclines induced the translocation of calreticulin (CRT) to the surface of cancer cells, leading to immunogenic cell death." (PMID 31780718, 2019). "In particular, the prognostic relevance of CALR expression levels or exposure on the membrane of cancer cells has been investigated by us and others in the context of multiple malignancies." (PMID 31747968, 2019). "Third, blockade of calreticulin led to complete abrogation of anti-CD47 antibody-mediated phagocytosis of cancer cells in vitro." (PMID 32038992, 2019). "Phagocytosis of cancer cells induced by calreticulin on their surface has been shown to result in presentation of antigens from the cancer cell on the phagocyte together with MHCII, resulting in an adaptive immune response to the cancer." (PMID 31781126, 2019). "Certain cancers present super-expression of surface calreticulin, but most normal cells have low calreticulin levels." (PMID 31709183, 2019). "While calreticulin can be induced on cancer cells, macrophages can also secrete calreticulin that binds to cancer cells leading to macrophage phagocytosis." (PMID 32038992, 2019). "First, cell surface calreticulin was expressed widely on multiple human cancers (AML, acute lymphoblastic leukemia, chronic myeloid leukemia, non-Hodgkin's lymphoma, bladder and ovarian cancer, and glioblastoma), but was absent on normal cell counterparts." (PMID 32038992, 2019).
cancer (continued). "Immunogenic cancer death is the process in which the dendritic cell recognizes the immune-adjuvant damage associated molecular patterns (DAMPs) like HGMB-1, calreticulin, and ATP and complements the cytotoxic cell death." (PMID 31015835, 2019). "This study reveals a novel role for the calcium-binding protein calreticulin in the survival of cancer cells; downregulation of calreticulin leads to mitochondrial calcium overload and an induction of non-apoptotic cell death." (PMID 31568485, 2019). "Dying cancer cells induced by PS-PDT or PD-PDT emit calreticulin, HMGB1 and ATP and they were efficiently engulfed by BMDCs, which then matured, became activated and produced IL-6." (PMID 31842994, 2019). "In past, others and we have demonstrated that, naturally occurring or artificially-induced, defects in ecto-CALR exposure, ATP secretion or HMGB1 release can cause cancer cells to resist the pro-immunogenic effects of ICD." (PMID 29707136, 2018). "Other ER chaperones, such as CALR, are regulated by the presence of ncRNAs whose promoters are hypermethylated in some cancer models." (PMID 29666625, 2018). "Here the authors show that, in mouse models, activated macrophages create an “eat me” signal via calreticulin secretion on neutrophils during peritonitis and on cancer cells, determining in both cases clearance by PrCR." (PMID 30097573, 2018). "The little information on the biological relevance of post-translational modification of CALR currently available limits our understanding of the contribution played by alterations of the post-translational modification sites of CALR in the etiology of cancer." (PMID 29218307, 2017). "RT can also induce immunogenic cancer cell stress or death and promote the transfer of calreticulin to cancer cell plasma membranes and the release of ATP and HMGB1." (PMID 28687760, 2017). "The major CALR defect described so far in cancer cells regards the levels of cell-surface expression." (PMID 29218307, 2017). "Investigating immunogenic cell death markers in cancer cells infected with recombinant VVs, we demonstrated that all tested recombinant VVs were efficient in calreticulin and HSP70 externalization, decrease of cellular HMGB1, and ATP secretion." (PMID 28951871, 2017). "Effects of different somatic SNPs most commonly found in cancer on the intrinsic disorder-based interactivity of human CALR." (PMID 29218307, 2017). "Recently it has become clear that most human cancer cells overexpress CD47 on their surface apparently to prevent themselves being phagocytosed; their phagocytosis being promoted by the presence of calreticulin on the surface of the cancer cells." (PMID 28977832, 2017). "Taken together, calreticulin is believed to be involved in the initiation and progression of various cancers." (PMID 27418879, 2016). "Calreticulin also participates in the immune response against apoptotic cancer cells, and surface exposure of CRT participates as an “eat me” signal required for phagocytosis on dying tumor cells." (PMID 27462315, 2016). "Here, mEHT increased calreticulin expression on the cell surface, likely promoting anti-cancer immune response." (PMID 27556507, 2016). "As calreticulin is also mainly involved in calcium homeostasis and protein chaperoning, several mechanisms can be proposed for its role in cancer initiation and progression." (PMID 27418879, 2016). "Radiation-induced immunogenic modulation of calreticulin in carcinoma cells is mediated by the endoplasmic reticulum (ER) stress response, as previously reported." (PMID 27893426, 2016). "We shed further light on this subject by showing that tumoural CALR expression is in fact a context-dependent predictive biomarker of anticancer therapy response in cancer patients." (PMID 26314964, 2015). "Other processes and parameters linked to CALR and/or HSP exposure and their immunostimulatory effects have been shown to influence disease outcome in cancer patients." (PMID 26300886, 2015).
cancer (continued). "The potential pro-immunogenic role of chaperones gained prominence by the discovery that cell surface exposure of calreticulin determines the immunogenicity of cancer cell death." (PMID 25688334, 2015). "Photodynamic therapy (PDT) belongs to cancer modalities capable of inducing an abundance of DAMPs including surface-exposed calreticulin." (PMID 25692097, 2015). "This review provides an in-depth look into the concepts and mechanisms underlying CALR exposure, activation of the Toll-like receptor 3/IFN/CXCL10 axis, and the release of ATP and HMGB1 from dying cancer cells." (PMID 26486085, 2015). "Clinical studies assessing the prognostic and predictive value of ICD-associated CALR and HSP signaling in cancer patients." (PMID 26300886, 2015). "Surface calreticulin expression on dying cancer cells is critical for their demise by immunological cell death (ICD) resulting in immune rejection of tumors with the same cells." (PMID 25692097, 2015). "CALR represents the most abundant protein in the ER lumen and gets translocated to the surface of stressed and dying cancer cells." (PMID 26486085, 2015). "Cell surface exposed calreticulin then promotes clearance of the dying cancer cells by DCs, with subsequent release of ATP, HMGB1, and HSP70 from late apoptotic cells giving requisite cues for DC maturation and clonal T-cell expansion." (PMID 25750898, 2015). "Here, we reviewed the biological roles of calreticulin and summarized the potential mechanisms of calreticulin in regulating mRNA stability and therefore contributed to cancer metastasis." (PMID 25918716, 2015). "Cancer therapy-mediated lethal insults that involve stress induction in the ER induce the translocation of calreticulin to the outer leaflet of the plasma membrane by an active process occurring before the appearance of morphological signs of apoptosis." (PMID 25692097, 2015). "It is clear from literature that treatment of cancer cells with TRAIL can induce calreticulin relocalization to the cell surface." (PMID 25750898, 2015). "Cell surface calreticulin is considered as an “eat-me” signal and promotes phagocytic uptake of cancer cells by immune system." (PMID 25918716, 2015). "In this context, it is worth noting that cancer cells exposing CALR, secreting ATP, producing type I IFNs but releasing limited amounts of HMGB1 as they respond to a lethal stimulus in a suboptimal manner fail to elicit adaptive immune responses." (PMID 25964783, 2015). "This activation of the immune system can be exploited via the injection of calreticulin-coated cancer cells." (PMID 25386408, 2014). "For instance, immunogenicity of apoptotic cancer cells has been attributed to the exposure of calreticulin, an endoplasmic reticulum chaperon, on the cell surface during early apoptosis." (PMID 24918927, 2014). "As well as the calcium-binding proteins, calreticulin and calnexin, were also previously detected in other cancer cells." (PMID 26269723, 2014). "Investigation of the proteins were associated with incidence of cancers, including ZAG, CALR, annexin A2, annexin A3 and Hp." (PMID 24884814, 2014). "The induction of ER stress in cancer cells by oxaliplatin or anthracyclines has been shown to induce calreticulin (CRT) localization outside the cell membrane, which mediates immunogenic apoptosis to stimulate tumor-specific CD8+ T cell responses." (PMID 25514597, 2014). "Collectively, these data indicate that increased sensitivity of carcinoma cells to T cell-mediated lysis is dependent upon the presence of calreticulin on the cell surface." (PMID 24480782, 2014). "Elevated expression of calreticulin has been reported in multiple cancers, and it is proposed that the upregulation of calreticulin seems to be induced by cellular stress from cancers." (PMID 23587357, 2013).